GPR132 (G protein-coupled receptor 132)
Diseases named in the same sentence as GPR132 in open-access papers (continued):
Sharing a sentence is not in itself a finding about the gene and the disease.
tumor (continued). "In the intricate landscape of the tumor microenvironment, the signal transduction triggered by lactate stimulation mainly relays on the lactate receptor HCAR1 (GPR81), and proton-sensing G-protein coupled receptors (GPRs), including GPR4, TDAG8 (GPR65), OGR1 (GPR68), and G2A (GPR132)." (PMID 38576043, 2024). "We found that Gpr132 was predominantly expressed in the hematopoietic cell types/tissues and highly expressed in macrophages, but largely absent in other tissues or tumor cells, indicating that it may play an important role in macrophage function." (PMID 27692066, 2016). "Nonetheless, our genetic rescue and pharmacological experiments indicate that Gpr132 is a very important part of the puzzle and an essential mediator of macrophage PPARγ regulation, because in the absence of Gpr132, the tumor-modulating function of macrophage PPARγ or rosiglitazone is abolished." (PMID 27692066, 2016). "In GPR132-KO mice, overexpression of THBS2 neither altered tumour volume nor affected the abundance of tumour-infiltrating CD8 + T cells and exhausted CD8 + T cells." (PMID 37884956, 2023).
cancer (23 papers, 2013 to 2025). A tumor composed of atypical neoplastic, often pleomorphic cells that invade other tissues. "Gpr132 expression was significantly higher in PPARγ-deficient macrophages compared with control macrophages, either in macrophage cultures alone or in macrophages co-cultured with cancer cells." (PMID 27692066, 2016). "Further, G protein-coupled receptor 132 (Gpr132) has been shown to function as a key macrophage sensor of the rising lactate in the acidic milieu to mediate the reciprocal interaction between cancer cells and macrophages." (PMID 36225935, 2022). "This Gpr132-dependent activity also resides in the <3-kDa fraction of cancer cell CM and is largely attributed to lactate." (PMID 35246504, 2022). "It has been demonstrated that cancer cell-deprived lactate is a Gpr132 activator which stimulates the macrophage M2 phenotype in a Gpr132-dependent manner." (PMID 35911719, 2022). "Another study showed that lactate released from cancer cells acts as ligand for G protein-coupled receptor 132 (Gpr132, a pH sensor) that converts macrophages to an immunosuppressive M2-like phenotype." (PMID 33968034, 2021). "Initial studies analyzing the putative role of GPR132 in cancer obtained opposite results on its influence of fibroblast transformation." (PMID 33113952, 2020). "We treated WT female mice with si-Gpr132 or si-Ctrl for 18 days via intravenous injection at 10 μg/mouse twice/week, three days before and 15 days after cancer cell graft." (PMID 27692066, 2016). "We next examined the function of macrophage Gpr132 in regulating cancer cells using our in vitro co-culture system." (PMID 27692066, 2016). "Future experiments will need to examine exactly how the Gpr132 proteins produced by macrophages communicate with the cancer cells." (PMID 27692066, 2016). "Recent studies show that the pH-sensing GPCRs, including GPR4, GPR65 (TDAG8), GPR68 (OGR1), and GPR132 (G2A), regulate cancer cell metastasis and proliferation, immune cell function, inflammation, and blood vessel formation." (PMID 24367336, 2013). "However, further investigation is warranted to validate the therapeutic potential of THBS2 and GPR132 in cancer." (PMID 37884956, 2023). "Considering the critical function of lactate modulating and shaping the immune cells, exploring the function of GPR132 not only conduces the understanding of the role of GPR132 in TME but also further reveals the elaborate carcinogenesis of lactate metabolism in cancer pathology." (PMID 36612084, 2022). "Therefore, our experiments were initiated in young mice and terminated before Gpr132-KO mice aged to prevent any potential effects of lymphoid defects on cancer growth." (PMID 27692066, 2016). "This uncovers Gpr132 as not only a novel key PPARγ target but also a new cancer therapeutic target." (PMID 27692066, 2016). "Conversely, Gpr132 over-expression in macrophages increased cancer cell growth." (PMID 27692066, 2016). "To further examine whether Gpr132 is a functional PPARγ target in macrophage that is required for PPARγ cancer regulation, we conducted pharmacological and genetic experiments." (PMID 27692066, 2016). "Gpr132 knockdown in macrophages significantly reduced cancer cell growth." (PMID 27692066, 2016). "Furthermore, developing new drugs that can inhibit Gpr132 could ultimately lead to more effective treatments for cancer." (PMID 27692066, 2016). "Studies in other models have shown that G2A/GPR132 is an oncogene; that is, 15-HETE through activation of G2A/GPR132 has a pro-cancer effect." (PMID 36765904, 2023). "A decrease in extracellular pH promotes growth, migration, invasion, and metastasis of cancer cells in an acidic environment via GPR4, GPR65 (TDAG8), GPR68 (OGR1), and GPR132 (G2A), which are pH-sensing G protein-coupled receptors (GPCRs)." (PMID 32998265, 2020). "Pre-treating Gpr132-KO macrophages with rosiglitazone before cancer cell seeding no longer showed any inhibition of cancer cell proliferation in the co-cultures." (PMID 27692066, 2016).
cancer (continued). "In this system, Gpr132 was deleted in macrophages as well as other Gpr132-expressing tissues such as bone marrow, spleen and thymus, but not in the injected cancer cells which had essentially no Gpr132 expression." (PMID 27692066, 2016).
hematological malignancies (1 paper, 2016). "Our identification of increased GPR132 levels in a subset of B-ALL adds to a growing body of evidence that GPCRs are aberrantly expressed in a spectrum of hematological malignancies." (PMID 27588474, 2016).
metabolic disease (1 paper, 2025). A congenital disorder (due to inherited enzyme abnormality) or acquired (due to failure of a metabolically important organ) disorder resulting from an abnormal metabolic process. "Furthermore, recent evidence indicates that macrophage‐specific knockout or inhibition of GPR132 enhances glucose homeostasis, indicating that GPR132 may be a critical target for metabolic diseases." (PMID 40492515, 2025).
GPR132 also shares sentences with these, for which no sentence is quoted: Autoimmunity (3 papers); autoimmune disease (2); basal cell carcinoma (1); blood cancer (1); cervicitis (1); coronary atherosclerosis (1); Ewing sarcoma (1); hematological cancer (1); infection (1); injury (1); metastatic melanoma (1); squamous intraepithelial lesions (1); systemic lupus erythematosus (1).